IFNG (interferon gamma)
Diseases named in the same sentence as IFNG in open-access papers (continued):
Sharing a sentence is not in itself a finding about the gene and the disease.
infection (continued). "However, although IL-17 receptor knockout mice were more susceptible to infection and also exhibited reduced inflammatory infiltration, the high levels of this cytokine observed in humans was not sufficient to generate IFNγ/NO levels that lead to natural recovery from VL." (PMID 29163510, 2017). "In each of these groups, the expression of IFNγ was higher in GFP-Egr2low cells than in GFP-Egr2high cells, consistent with the results from infection of GFP-Egr2 mice." (PMID 28487311, 2017). "Our results, illustrated in a graphical summary, suggest that IFNG and IL22 were acutely upregulated in response to C. trachomatis infection and expression appeared to be reduced following the clearance of infection, despite the persistence of inflammation." (PMID 28966918, 2017). "IL10 production by IFNγ+ CD4 T cells was higher in younger children and in those with high-parasite burden during recent infection." (PMID 29097996, 2017). "When severe clinical neurological signs appeared, the expressions of iNOS, IFNG, ILB, IL6, and IL8 genes were elevated dramatically in the brain following the very virulent plus (vv+) GaHV2 infection, especially at 10 and 14 dpi28." (PMID 28912500, 2017). "cNK cells were stimulated ex vivo after 5 days of infection with anti-NK1.1 and stained intracellularly for IFNγ production." (PMID 27721814, 2016). "In a mouse model of infection, TLR7/9 were required for optimal production of IFN-I and IFNγ, host survival, and restriction of cerebral fungal burden." (PMID 27459510, 2016). "Significant increases in IFNA, IFNG and TLR3 mRNA expression are reported during HPAI infection of chicken dendritic cells." (PMID 27071061, 2016). "IFNγ came up in both gene set enrichment analyses, IPA and CMAP, suggesting that TBEV induces IFNγ after infection in astrocytes." (PMID 27776548, 2016). "After infection with γHV-68, Sh2d1a−/− mice have an expanded population of CD8+ T-cells, which produce higher levels of IFNγ as compared to CD8+ T-cells from infected WT mice." (PMID 26834746, 2016). "Early after infection, many of the ESAT6-specific CD4+ T cells were polyfunctional based on their production of IL-2, IFNγ, and TNF." (PMID 26967901, 2016). "To determine if CD8+ T-cells were functioning normally in HD mice, we measured the number of IFNγ+ CD8+ T-cells in HD and wild-type infected mice at 15 days post infection." (PMID 27611938, 2016). "Both zebrafish IFNγ orthologs—ifng and ifng—were induced largely in a RAG-dependent fashion at 6 weeks post-infection in adult zebrafish." (PMID 27512905, 2016). "In accordance with reports on γHV-68 infected Sh2d1a−/− mice, LCMV-Armstrong infections induce a stronger expansion of CD4+ and CD8+ IFNγ-producing T-cells." (PMID 26834746, 2016). "During infection with Mycobacterium avium or LCMV, IFNγ increased HSC proliferation and led to a reduction in transplantable myeloid potential." (PMID 27621733, 2016). "The expression of genes encoding other cytokines were also significantly increased during infection, including the pro-inflammatory cytokines IL1, IL8, tumor necrosis factor alfa (TNF-α), interferon gamma (IFN-γ), and CSF2." (PMID 27982111, 2016). "Due to infection of macrophages with AG83+Sias, reduction of the genetic expression of Th1 cytokine genes (IFNγ and IL-2) and upregulation of Th2 cytokine genes (IL-4, IL-10 and TGFβ) were observed." (PMID 27494323, 2016). "We used IFNγ activated BMDM’s resembling inflammatory monocytes, whose primary immune function is bacilli killing during infections." (PMID 27995986, 2016). "The levels of IFNγ,IL-12/IL-23 p40, IL-1β, CXCL1/KC as well as the expression of CXCR2 wereincreased in the lung of M-TNFR1 KO as compared with TNFR1 KO 3 weekspost-infection, and further increased in both groups at 4–5 weeks." (PMID 26931771, 2016). "After anti-CD3/CD28 mAb stimulation, TIM3+PD1– T cells produced more IFNγ and TNF than other T cells even late during infection." (PMID 26967901, 2016).
infection (continued). "AG83+Sias-infected macrophages produced significantly (p≤ 0.05) less IFNγ level which was enhanced when AG83-Sias or UR6 (p≤ 0.01 and p≤ 0.001) were used for infection." (PMID 27494323, 2016). "In particular, IFNγ is required for long-term control of neurotropic viruses in CD46+ adult mice and other infection models." (PMID 27178303, 2016). "Ad5 replication was inhibited by both IFNα and IFNγ in single knockdown cells, as well as in the control cells, despite high MOI infection (left)." (PMID 26809031, 2016). "At day 9 after LCMV-Cl13 infection of IFNγR-/- mice, the number of total splenocytes was decreased ~10-fold compared to WT mice and this corresponded with a similar 10-fold decrease in the amount of total DC and stimDC, suggesting that loss of IFNγ does not specifically affect stimDC maturation." (PMID 26808628, 2016). "IFNγ levelswere similar in T-TNFR1 KO and WT mice, although they were highly elevated inthe lungs of M-TNFR1 KO mice, 5 weeks after infection." (PMID 26931771, 2016). "During systemic bacterial infections, activated NK cells can limit tissue infection and prevent systemic spread of the pathogen through direct lysis of target cells or by releasing GM-CSF, TNF and IFNγ to orchestrate further responses." (PMID 27341123, 2016). "Given their overlapping tissue tropism, it is possible that infection of a rare HR-HPV positive cell can protect C. trachomatis against antibiotic-mediated clearance, especially during a robust IFNγ-dependent protective immune response." (PMID 27658027, 2016). "Infection with EBOV/VP35m infection resulted in a significant increase, as compared to wt EBOV, in proliferating CD4+ cells secreting IFNγ, TNFα and IL-2." (PMID 27930745, 2016). "When given in the first 3 days of infection, treatment with E6446 inhibited CD4+ and CD8+ T-cell activation and IFNγ production." (PMID 27808089, 2016). "Based on transcriptional analysis studies, infection with virulent strains of NDV induces transcriptional upregulation of numerous cytokines, such as interferon alpha (IFN-α), interferon gamma (IFN-γ), interleukin 8 (IL-8), and interleukin 2 (IL-2)." (PMID 26253150, 2015). "ECM, the pathological outcome of experimental infection with P. berghei ANKA in C57BL/6 mice, is a result of IFNγ production and CD8+ T cell infiltration into the CNS." (PMID 25884830, 2015). "The effect of these alleles on resistance to infection has not been reported; however, high levels of IFNγ have been associated with resistance to infection, suggesting that the low prevalence of the 2109G fibrosis risk allele in African populations may be protective against infection." (PMID 26540410, 2015). "S. aureus antigen-specific IFNγ-producing CD4+ (Th1) cells are expanded in both humans and mice following infection, and these cells are definitively protective in mice." (PMID 26539822, 2015). "Nevertheless, IFNγ+ cells, either by producing IFNγ or any other effector molecules and/or by other mechanisms, may play a dual role in the CNS, shutting down the high parasite burden in the acute infection, while fueling low parasitism in the chronic phase of infection." (PMID 25695249, 2015). "To further assess the functional implications of our observations in the acquisition of innate effector functions in the context of acute Listeria monocytogenes (LM) infection, we analysed IFNγ expression in WT and IRF9−/− mice 16 h post infection." (PMID 25953241, 2015). "Blood-stage parasites are however recognized in human volunteers, which was demonstrated by an earlier increase of IFNγ and monokines induced by IFNγ (MIG) concentrations in CPS immunized volunteers compared to infection controls after direct blood challenge." (PMID 25714922, 2015). "Consistent with the observation at primary infection, rA2-19F reinfection increased the frequency of IL4 expressing CD4+ T cells (15.54 ± 1.70 vs. 8.33 ± 0.82 %) and decreased the frequency of IFNγ expressing CD4+ T cells (31.46 ± 2.41 vs 48.08 ± 3.24 %)." (PMID 26231396, 2015).
infection (continued). "This opposed the DTH theory and suggested that a Th2 response either was ineffectual at clearing infection or led to enhanced pathology and that CD4+ Th1 IFNγ responses were a key element of protective immunity in trachoma." (PMID 26424969, 2015). "In the context of EBOV GP/rVSV infection, delivery of IRF1 siRNA containing exosomes knocked down IRF1 mRNA levels by approximately 50% in both M-CSF- and M-CSF/IFNγ-treated macrophages." (PMID 26562011, 2015). "In contrast to the infection specific memory response to LF domain IV, initial exposure to the same antigen in the context of the AVP vaccine, led to a focused Th1 IFNγ response." (PMID 26075052, 2015). "By day 6 post infection, a shift occurred and CD4 and CD8 T cells were the majority of IFNγ producing cells in the spleen." (PMID 26070118, 2015). "IDO can be induced in most human cells, especially antigen-presenting cells (APCs), by inflammatory cytokines such as interferon gamma (IFNγ), tumor necrosis factor (TNF)-α, and infection." (PMID 26579709, 2015). "Consistent with reduced morbidity and mortality in the EBOV GP/rVSV infected, IFNγ-treated mice, mice treated with 3.3 μg of IFNγ at 24 hour before infection had dramatically lower EBOV GP/rVSV viremia at day 2 of infection." (PMID 26562011, 2015). "Splenocytes of P. falciparum-infected monkeys stimulated with P. falciparum-pRBCs showed increased expression levels of IFNγ, IL6 and IL12 on d7 of infection." (PMID 25890318, 2015). "Antiviral genes, including IFNA, IFNG, MX1, IFITM1, IFITM3, and IFITM5, were upregulated in response to infection." (PMID 25505077, 2015). "The production of pro-inflammatory cytokines, such as IL-12, are essential to develop a T helper 1 response, characterized by the presence of large amounts of interferon gamma (IFN-γ), which protects against infection." (PMID 26659253, 2015). "In this study, primers for quantitative real time PCR for Saimiri IFNγ, TNFα, IL2, IL6, IL10, and IL12 were validated and used in a study of splenic responses in S. sciureus during blood infection by P. falciparum." (PMID 25890318, 2015). "In contrast, 24 weeks of infection induced new changes in other inflammatory molecules with reduced KC, MCSF, enhancing GM-CSF, IFNγ, IL-1β, IL-13, IL-4, IL-13, lymphotactin, RANTES, and also an increase in select inflammatory molecules." (PMID 26619277, 2015). "The splenic results agree with an earlier report showing significantly increased IFNγ levels in the serum and increased CD8+ T cells expressing IFNγ in IL-15 Tg mice after infection with mycobacterium bovis bacillus Calmette-Guérin." (PMID 26600079, 2015). "Results of ICS indicate a significant increase in IFNγ- and IL-17A-producing Prn-, FHA-, and Ptx-specific CD4+CD44+ T-cells after infection." (PMID 25137043, 2014). "Statistically significant increases in total percentages of CD4+IFNγ+, CD4+IL-2+, and CD4+TNFα+ T cells were detected post-infection relative to D0 (P<0.05, 0.01, and 0.05, respectively) following primary infection." (PMID 25397604, 2014). "These cells are activated later during the infection process, but persist longer than type I IFN secreting cells and both have the potential to secrete IFNγ, and thus control lytical CMV replication." (PMID 24586165, 2014). "Soon after infection and ensuing inflammation (type I IFN and IL-12), resident NK cells respond, produce IFNγ and TNFα, and become cytotoxic." (PMID 25197644, 2014). "IFNγ producing CD4 and CD8 T cells were detected at a higher frequency and much earlier during secondary infection as compared to primary infection in the same chimpanzees." (PMID 24982656, 2014). "Serum IL-6, IL-10, and IFNγ continued to increase during the clinical course; IP-10 and MCP-1 remained at a high level from the beginning of infection." (PMID 25003343, 2014). "High levels of IFNγ are secreted by Type 1 T helper cells (Th1 cells), CD8+ cytotoxic T lymphocytes (CD8+ CTLs), and NK cells during active infection." (PMID 24454311, 2014).
infection (continued). "As with many infections, NK cells respond to both type I IFN and IL-12 during Mtb infection resulting in their production of IFNγ and are critical for early survival in the mouse model as demonstrated in RAG2−/− common-γ-chain−/− and IL-12p40−/− mice." (PMID 25197644, 2014). "To assess the impact of differential IFNγ production on MCMV replication, we investigated viral titers in the spleens of BcA mice 3 days post infection." (PMID 25473962, 2014). "In line with the observations made using the WBA, an increase in IFNγ was observed in supernatants of 73% of SA cultures following stimulation with SLA, indicating that antigen specific cells are present at the site of infection." (PMID 25275531, 2014). "On day 8 post-infection, PbT-I cells were recovered from the spleen and briefly restimulated with anti-CD3 mAb to test for production of IFNγ, TNFα and CD107a, the latter of which is a surrogate marker for degranulation." (PMID 24854165, 2014). "Taken together, these data demonstrate that Toxoplasma pre-infection of BMDC leads to synergistic activation and binding of atypical STAT1 complexes to GAS sequences in response to IFNγ." (PMID 23527309, 2013). "Since the FV-specific CD8 T cell response influences the FV load during acute infection, we quantified the FV-specific CD8 T cells after NK1.1+ cell depletion or IFNγ blockade in persistently mCMV infected mice." (PMID 23738889, 2013). "In our study P2X7R activation in APCs was able to reduce the activation of CD8+ cells to produce IFNγ by ∼ 50%, and this decrease was similar to the reduction of the activation of CD8+ cells found after APCs infection." (PMID 23940597, 2013). "To quantify the effects of HIV on NK-cell function, we assessed NK cell degranulation and interferon-gamma (IFN-γ) secretion in paired blood samples collected prior to HIV acquisition and after infection, during the early stages of primary infection." (PMID 23326405, 2013). "This study demonstrates that systemic levels of some cytokines, more specifically IFNγ, IP-10, MIG and MCP-1, rapidly and specifically change upon starting TB chemotherapy only in the presence of infection in a mouse model." (PMID 23469125, 2013). "However, recent data suggests that CD4-DN-TGFβRII mice display high levels of IFNγ level during intestinal helminth infection which, given the known role of IFNγ in promoting chronic T. muris infection, may explain the enhanced levels of infection observed in CD4-DN-TGFβRII mice." (PMID 24098124, 2013). "The induction of interferon gamma (IFN-γ) and response to it in these infections has received considerable attention." (PMID 23801993, 2013). "Following secondary infection, fgl2−/− mice displayed both higher frequency and number of virus-specific CD8+IFNγ+ T cells compared to fgl2+/+ mice at all time points examined." (PMID 24146739, 2013). "At effector time points following Lm-gp61 infection, both WT and bim−/− SMARTA cells were capable of making IFNγ upon restimulation." (PMID 23840678, 2013). "In IFNγ−/− neonatal mice, the recruitment of CD103+DC was dramatically altered despite a higher level of infection." (PMID 24367259, 2013). "Gene expression studies have shown increased expression of IFNγ, IL12p40, Perforin, IDO, IL-4, IL-10, and forkhead box p3 (FOXP3) in infection and/or disease, with levels generally being highest if both were present." (PMID 23457650, 2013). "Cytokines, such as interferon gamma (IFN-γ) and tumor necrosis factor alpha (TNF-α), secreted by NK cells at early stages of infection mediate inflammatory responses in inflamed tissues and also coordinate with DCs to induce Th1 cell polarization." (PMID 24147080, 2013). "During the third phase from day 5 until day 15 post-infection, transcriptional regulators STAT1 and STAT3 are highly expressed, together with IFNγ characteristic of CD4 T-lymphocyte activity." (PMID 23687968, 2013).
infection (continued). "On day 7 post infection, we quantified SIINFEKL-specific CD8+ αβ T cells by intracellular IFNγ staining." (PMID 23671671, 2013). "By 8 weeks of infection, the production of IL-4 and other TH2 cytokines predominates and IFNγ is barely detectable." (PMID 23429492, 2013). "C57BL/6 mice were infected with VACV WR by the intraperitoneal route (i.p.)and 7 days after infection, the percentage of CD8+ T cells responding to ex vivo stimulation with each peptide was determined by intracellular staining for IFNγ." (PMID 23382674, 2013). "We concluded that the IFNγ-ICS assay is highly reproducible and that substantial differences can exist in responses of different mice to the same epitopes in the same infection." (PMID 22745779, 2012). "QFT relies on M.tuberculosis (MTB) specific T-cell responses, measuring levels of interferon-gamma (IFN-γ) released in whole blood in response to stimulation with the MTB specific antigens: ESAT-6, CFP-10 and TB7.7, indicating past or present infection." (PMID 22808002, 2012). "Microarray gene expression was confirmed by real-time quantitative PCR for a subset of12 genes, which revealed that IFNG HIF1A and TNFA, among others, were significantly differentially expressed between the two strains at day 14 post-infection." (PMID 23006927, 2012). "A low proportion of peripheral blood CD8+IFNγ+ cells were CCR5+LFA-1+, whereas a high proportion of CD8+Pfn+ cells were CCR5+LFA-1+ during the acute (45 dpi) and chronic (120 dpi) phases of infection." (PMID 22532799, 2012). "IL-27 plays a role in the development of IFNγ+IL-10+ CD4+ T cells during experimental L. major and Listeria monocytogenes infection in vivo, as assessed using IL-27Rα−/− mice." (PMID 22911108, 2012). "The analysis of CD8+ T-cells in the peripheral blood revealed that most of the IFNγ+ cells were CD8+IFNγ+IL-10+ in the acute and in the chronic infection and accumulated in blood in the chronic phase of infection." (PMID 22532799, 2012). "In vitro infection of J774A.1 macrophages with RSV induced an alternatively activated macrophage (AAM) phenotype however, when macrophages were first primed with IFNγ, a CAM phenotype was induced and RSV spread to adjacent Hep-2 cells was reduced." (PMID 22792355, 2012). "Inflammatory cytokines, such as IFNγ, interleukin (IL)-6 and TNFα, and the chemokines, CCL2 and CCL5, were highly upregulated in the respiratory tract after infection with 12500 EID50." (PMID 22496659, 2012). "Four animals were sacrificed 2, 4, 7, 10, 16, and 21 days after infection to obtain the serum for cytokines quantification (TNF, IFNγ, and IL-10)." (PMID 22666132, 2012). "Based on our findings that the ratio of IL-4 to IFNγ was greater in neonatal compared to adult animals following RSV infection, we sought to compare age-dependent AM phenotypes following RSV- or mock-infection." (PMID 22792355, 2012). "Wt mice had mild disease and infection, mounting a sufficient early innate response and a subsequent influx of activated CD4+ and CD8+ T-cells, effective release of Chlamydia-specific IFNγ and proliferation of mediastinal lymph node T-cells." (PMID 22724018, 2012). "We therefore analyzed the effect of infection with an RH(I), Pru(II), or CEP(III) strain on IFNγ induced transcription using microarray analysis." (PMID 23240025, 2012). "Our data also showed a correlation between the amounts of triple positive IL-2+TNFα+IFNγ+ vaccine-specific CD4 T cells induced by immunization and the subsequent level of protection against infection with M.tb." (PMID 22768165, 2012). "Greater expression of IFNG and IL17A were detected in DBA/2 mice at day 15 post-infection using the Mouse Common Cytokines Gene Array." (PMID 23006927, 2012). "In the circulating blood, there was a predominance of CD8+IFNγ+ cells in comparison with CD8+Pfn+ cells during the acute (45 dpi) and chronic (120 dpi) phases of the infection." (PMID 22532799, 2012).